CD38 (CD38 molecule)
Diseases named in the same sentence as CD38 in open-access papers (continued):
Sharing a sentence is not in itself a finding about the gene and the disease.
osteosarcoma (2 papers, 2022 to 2024). A usually aggressive malignant bone-forming mesenchymal neoplasm, predominantly affecting adolescents and young adults. "The research also identified a negative association between CD20+CD24+CD27+ B cells and CD20+IgD+CD38− B cells with osteosarcoma risk." (PMID 39081321, 2024). "CD20 on IgD+ CD38− B cells also have a similar impact on osteosarcoma (OR: 0.19 [95% CI: 0.05 to 0.68], p = 0.011), and the weighted median method supported it." (PMID 39081321, 2024). "Our findings found that CD80 on CD62L+ myeloid dendritic cells and CD28−CD4−CD8− T-cell absolute count are positively associated with OS, and CD20 on CD24+CD27+ B cells and CD20 on IgD+ CD38 B cells have a negative effect on osteosarcoma." (PMID 39081321, 2024).
osteosclerosis (2 papers, 2022 to 2025). Abnormally high bone density. "Consistent with findings in vitro, CD38 blockage via CD38 inhibitor injection protected against osteosclerosis in medial subchondral bone and cartilage degeneration in DMM‐induced experimental mice." (PMID 35441488, 2022).
ovarian serous cancer (2 papers, 2020 to 2021). "This analysis revealed that CD38 mRNA was more highly expressed in malignant EOC than in borderline tumors, and ovarian endometrioid carcinoma had lower CD38 expression than ovarian serous cancer." (PMID 32425977, 2020).
papillary thyroid cancer (2 papers, 2021 to 2024). "In our previous study on the function of peripheral blood T cells in patients with papillary thyroid cancer, our team found that CD38 and HLA-DR molecules were increased in peripheral blood T cells of patients with papillary thyroid cancer and were associated with lymph node metastasis." (PMID 34465342, 2021).
parasitemia (2 papers, 2021 to 2023). "Increased parasitemia during peak infection was associated with increased cell frequency and expression of CD38, ICOS and CD86 by Vδ2+ T cells and increased CD86 and HLA-DR by Vδ1+ T cells." (PMID 37968278, 2023).
Peritoneal Fibrosis (2 papers, 2023). Disorder characterized by a wide range of structural changes in PERITONEUM, resulting from fibrogenic or inflammatory processes. "This was consistent with a recent study demonstrating that targeting CD38-dependent NAD+ degradation mitigates skin, lung, and peritoneal fibrosis." (PMID 36804530, 2023).
peritonitis (2 papers, 2022 to 2024). Inflammation of the peritoneum (tissue that lines the abdominal wall and covers most of the organs in the abdomen). "Moreover, sUA at physiological levels prevents crude lipopolysaccharide (cLPS)-induced systemic inflammation and monosodium urate (MSU) crystal-induced peritonitis in mice by interacting with CD38." (PMID 39527634, 2024).
pertussis (2 papers, 2024). A contagious bacterial respiratory infection caused by Bordetella pertussis. "Compared to iHUU, iHEU had elevated CD56loCD16loPerforin+CD38+CD45RA+FcεRIγ+ NK cells at 1 month postpartum and whose abundance pre-vaccination were predictive of vaccine-induced pertussis and rotavirus antibody responses post 3 months of life." (PMID 38744812, 2024).
POEMS syndrome (2 papers, 2022 to 2024). POEMS syndrome is a paraneoplastic syndrome characterized by polyradiculoneuropathy (P), organomegaly (O), endocrinopathy (E), clonal plasma cell disorder (M), and skin changes (S). "To examine the difference in CD38 expression between monoclonal and normal PCs in POEMS syndrome, we analyzed CD38 mean fluorescence intensity (MFI) in 18 cases where monoclonal PCs were detected by POEMS-flow." (PMID 38710832, 2024). "Also, this study revealed that CD38 MFI is significantly lower in monoclonal PCs of POEMS syndrome compared to normal PCs." (PMID 38710832, 2024). "Therefore, despite the reduced CD38 expression in POEMS PCs, POEMS-flow is suitable for detecting clonal PCs in POEMS syndrome." (PMID 38710832, 2024). "We employed EuroFlow-NGF-based single-tube eight-color multiparameter flow cytometry (MM-flow) and established a new gating strategy (POEMS-flow) to detect the monoclonal PCs in POEMS syndrome, gating CD38 broadly from dim to bright and CD45 narrowly from negative to dim compared to MM-flow." (PMID 38710832, 2024). "Another anti-CD38 immunotherapy isatuximab which is approved for relapsed/refractory MM may also be effective in the treatment of POEMS syndrome but its use in POEMS syndrome has not yet been reported." (PMID 36498588, 2022). "Conclusively, this study evaluated the sensitivity of EuroFlow-NGF-based MFC in detecting clonal PCs in POEMS syndrome and demonstrated the usefulness of the optimized POEMS-flow, gating CD38 broadly from dim to bright and CD45 narrowly from negative to dim compared to EuroFlow-NGF-based MFC." (PMID 38710832, 2024).
renal failure (2 papers, 2022 to 2023). "Additionally, they found a correlation between CD38+ HLA-DR+CD4+ T cells and ferritin, renal insufficiency, acute kidney disease, and APACHE III score, indicating a relationship between disease severity and activation of CD4+ T cells." (PMID 36675642, 2023).
sarcopenia (2 papers, 2019 to 2021). Progressive decline in muscle mass due to aging which results in decreased functional capacity of muscles. "In contrast, no increase in the expression of NAD+ consuming enzymes such as CD38, PARPs or sirtuins was observed, suggesting that reduced NAD+ levels in human sarcopenia primarily result from inability to synthesize and recycle NAD+." (PMID 31862890, 2019).
seminoma (2 papers, 2015). A radiosensitive malignant germ cell tumor found in the testis (especially undescended), and extragonadal sites (anterior mediastinum and pineal gland). "The characteristics of hPGCLCs are consistent with the embryonic hPGCs and a germline seminoma that share a CD38 cell-surface marker, which collectively defines likely progression of the early human germline." (PMID 25543152, 2015). "CD38, a novel cell surface marker of human germline, is shared by a seminoma cell line, as well as by gonadal hPGCs." (PMID 26028529, 2015). "We found that CD38 is a marker of all human germline-related cells, including seminomas." (PMID 25543152, 2015). "Transcriptome analysis of hPGCLC and comparison with authentic in vivo wk7-wk9 hPGCs, and a seminoma cell line showed that they shared expression of key PGC genes, among which were SOX17 and a cell surface marker CD38." (PMID 26028529, 2015).
Sézary Syndrome (2 papers, 2022 to 2025). "Previous investigations on CD38 expression in CTCL have been limited and somewhat inconsistent, particularly in Sézary Syndrome (SS) cells, which exhibited intermediate CD38 staining in treatment-resistant, aggressive CTCL subtypes." (PMID 40057636, 2025).
T-cell leukemia (2 papers, 2023). A malignant disease of the T-lymphocytes in the bone marrow, thymus, and/or blood. "Furthermore, trans-retinoic acid combined with interferon-α disrupts the metabolism of CD38 malignant cells, increasing their sensitivity to anti-CD38 antibodies in T cell leukemia." (PMID 36679026, 2023).
thoracic cancer (2 papers, 2022 to 2023). A primary or metastatic malignant neoplasm affecting the tissues of the thorax. "Given the significant roles played by both T-bet and CD38 in immunosenescence, our data provide insights into the cellular and molecular mechanisms linking RT-induced p90RSK activation, immunosenescence, T-bet, and CD38 induction observed in thoracic cancer patients undergoing RT." (PMID 37781317, 2023).
thyroid cancer (2 papers, 2020 to 2025). "There are very few studies till date that have reported on the correlation of CD38+ T cells HLA-DR+ and thyroid cancer." (PMID 32050977, 2020).
typhoid fever (2 papers, 2017 to 2020). A bacterial infectious disorder contracted by consumption of food or drink contaminated with Salmonella typhi. "Regardless of the dose, we found that challenge elicited increased levels of activated MAIT cells (either CD38+ single positive or CD38+HLA-DR+ double positive) in TD volunteers, a phenomenon that was associated with the time of TD (48 and 96 h after diagnosis of typhoid fever)." (PMID 28428786, 2017). "However, during typhoid fever, we found higher levels of activated (CD38+) proliferating MAIT cells in TD volunteers receiving a low dose than in those TD volunteers receiving a high dose of the inoculum." (PMID 28428786, 2017). "Here, we report that activated (CD38+) MAIT cells coexpressing CCR6 and CCR9 markers were significantly higher during typhoid fever in TD volunteers receiving the low-dose inoculum than in TD volunteers receiving the high-dose inoculum." (PMID 28428786, 2017). "Interestingly, MAIT cells from low-dose TD volunteers had higher levels of CD38 coexpressing CCR9, CCR6, and Ki67 during the development of typhoid fever than high-dose TD volunteers." (PMID 28428786, 2017). "Interestingly, we found that TD volunteers exposed to low doses of wild-type S. Typhi (103 CFU) had higher levels of CD8+ MAIT cells coexpressing CD38 and either CCR9, CCR6, or Ki67 during the development of typhoid fever than TD volunteers receiving a high dose of S. Typhi (104 CFU)." (PMID 28428786, 2017). "Similar to the expression of CD38 and HLA-DR markers and regardless of the dose, we found high levels of MAIT cells expressing CD57 and caspase-3 markers in TD volunteers after typhoid fever diagnosis." (PMID 28428786, 2017).
ulcers (2 papers, 2024 to 2025). "In C57BL/6 mice with ulcerative disease, activated CD38+CD8+ cells were significantly more numerous in DLNs of low-dose mice compared to both controls and high-dose mice." (PMID 40823822, 2025). "In the same context, the current study found that the M1 macrophage markers CD38 and CD86 increased as a response to ethanol-induced ulcers." (PMID 39314751, 2024).
urothelial carcinoma (2 papers, 2020 to 2022). A malignant neoplasm derived from the transitional epithelium of the urinary tract (urinary bladder, ureter, urethra, or renal pelvis). "In conclusion, these data demonstrate the importance of CD38 for tumor progression and suggest CD38 as a treatment for uroepithelial carcinoma." (PMID 35725444, 2022). "To test whether CD38 is the target for the treatment of urothelial carcinoma, we establish the MB49 subcutaneous xenograft model in C57BL/6 mice." (PMID 35725444, 2022). "In urothelial carcinoma, CD38 is more widely expressed than PD-1, suggesting that targeting CD38 may be more effective than targeting PD-1." (PMID 35725444, 2022). "CD38 may be a more suitable target for immunotherapy in urothelial carcinoma compared to PD1/PDL1." (PMID 35725444, 2022). "CD138 and CD38, which are immunohistochemical markers for plasma cells, showed opposite immunostaining, and this noninvasive urothelial carcinoma was positive for CD138 and negative for CD38." (PMID 33032610, 2020). "The coexpression of activation molecules (HLA-DR, CD38) and co-inhibitory molecules (PD-1, CTLA-4) represents the T cell exhaustion, the results showed that almost all clusters had exhaustion phenotype in the immune microenvironment of urothelial carcinoma tissues." (PMID 35725444, 2022).
abscess (1 paper, 2022). An inflammatory process characterized by the accumulation of pus within a newly formed tissue cavity which is the result of a bacterial, fungal, or parasitic infection or the presence of a foreign body. "Cd38-/- mice had significantly smaller abscesses on d3 p.i. and a significantly lower level of proinflammatory monocytes (similar to naïve mice)." (PMID 36010615, 2022). "Assuming that CD38+ROS+ monocytes are responsible for immunopathological mechanisms during the early phase of hepatic amebiasis, genetic deletion of CD38 should lead to smaller abscesses." (PMID 36010615, 2022). "Next, we used knockout mice lacking CD38 to investigate whether CD38+Ly6Chi monocytes contributes to abscess formation during E. histolytica liver infection." (PMID 36010615, 2022).
adenoma (1 paper, 2024). A neoplasm arising from the epithelium. "Furthermore, the percentage of antibody-secreting CD19+CD38+CD27+ plasma cells also decreased in the adenoma grade II group (2.775 vs. 0.405, P < 0.0001), adenoma grade III group (2.775 vs. 1.230, P = 0.0015), and CRC group (2.775 vs. 1.280, P = 0.0155) compared with that in the control group." (PMID 38343544, 2024).
Alexander disease (1 paper, 2019). Alexander disease (AxD) is a rare neurodegenerative disorder of the astrocytes comprised of two clinical forms: AxD Type I and Type II manifesting with various degrees of macrocephaly, spasticity, ataxia and seizures and leading to psychomotor regression and death. "By introducing Alexander disease (AxD)-associated hotspot mutations (R79C, R239C) into GFAP gene of hPSCs and subsequently inducing astrocyte differentiation, we found that GFAP mutations impaired mitochondrial transfer from astrocytes and reduced astrocytic CD38 expression." (PMID 31327963, 2019).
allergic conjunctivitis (1 paper, 2019). "Our findings demonstrate an immunological dysregulation in patients with allergic conjunctivitis, characterized by the low expression of IL-10 in circulating CD19+CD38+ Bregs subsets, and an inverted tear IL-10/TNF-α ratio." (PMID 30818819, 2019). "Our findings demonstrate an immunological dysregulation in patients with allergic conjunctivitis, characterized by the low expression of IL-10 in circulating CD19+CD38+ Bregs subsets and an inverted tear IL-10/TNF-α ratio, promoting a local pro-inflammatory microenvironment." (PMID 30818819, 2019).
aneurysm (1 paper, 2021). Bulging or ballooning in an area of an artery secondary to arterial wall weakening. "Most importantly, our findings suggest the potential usefulness of the circulating levels of IgG, CD38 and GDF15 to assist AAA management in conjunction with aneurysm diameter and/or PWS during the follow-up of these patients." (PMID 33919749, 2021).
Atherosclerotic lesion (1 paper, 2025). A lesion associated with atherosclerosis, a multifactorial and multipart progressive disease manifested by the focal development within the arterial wall of lesions, that ranges from the development of a fatty streak, plaque progression, and plaque disruption. "Interestingly, IL-1R2 has been found to be reduced in monocytes and macrophages in atherosclerotic lesions, whereas we find that the CD38+ TIM subclusters are enriched for IL-1R2." (PMID 40327401, 2025).
avian influenza (1 paper, 2014). Infection of domestic and wild fowl and other birds with influenza A virus. "In this study, we found significantly higher frequencies of CD38 + CD4+, CD38 + CD8+, Tim-3 + CD4+ and Tim-3 + CD8+ T cells in patients with H7N9 avian influenza compared with those in the HCs." (PMID 25030090, 2014).
basal cell carcinoma (1 paper, 2013). A carcinoma involving the basal cells. "Data moreover imply CD38 as a target for anti-angiogenic therapy of human basal cell carcinoma." (PMID 23308177, 2013). "Therefore, the distribution of CD38 was studied on cryosections of biopsies from fibrotic scleroderma and neovascularised human basal cell carcinoma (BCC) patients." (PMID 23308177, 2013). "Moreover, CD38 signaling modulates PECAM1+/Sca1+/CD38+ cell activation in the healing process implying CD38 as a target for anti-angiogenic therapies in human basal cell carcinoma." (PMID 23308177, 2013). "Interestingly, in human basal cell carcinoma (BCC) PECAM1low/CD38+ cells are mainly found in the highly vascularized tumor stroma in regions of newly formed vascular sprouts, whereas most of the mature PECAM1high vessels lack CD38 expression." (PMID 23308177, 2013).
behavior problems (1 paper, 2020). "Previous studies have found that maternal oxytocin level may be determined by CD38 and oxytocin receptor gene polymorphisms (e.g., OXTR rs53576), which are associated with child behavior problems." (PMID 32581866, 2020).
biliary cirrhosis (1 paper, 2011). "Positive controls showed CD38+ inflammatory cells adjacent to biliary cirrhosis in hepatic tissue sections." (PMID 21850166, 2011).
biliary tract cancer (1 paper, 2024). "The IVW analysis of CD25 on IgD+ CD38- naive (OR=1.08, 95% CI=1.01–1.16, P=0.025) indicated an increased risk of biliary tract cancer." (PMID 39050844, 2024). "Within the phenotype of immune cells expressing CD20 on CD20- CD38-, B cells exert a protective effect against biliary tract cancer risk, whereas cells lacking CD20 expression such as CD20- AC and CD27 on CD20- CD38- promote the risk of biliary tract cancer." (PMID 39050844, 2024).
B‐cell deficiencies (1 paper, 2025). "In addition, the CD38 peptide vaccine may provide additional benefits for patients with congenital or acquired B‐cell deficiencies." (PMID 40557469, 2025).
Castleman disease (1 paper, 2025). Castleman disease (CD) is a benign lymphoproliferative disorder that may present as a localized or multicentric form. "Lymph node pathology revealed an increase in IgG4-positive cells, with a high number of CD38 and CD138 plasma cells, and the morphology was consistent with Castleman disease (plasmacytic type)." (PMID 40696682, 2025). "A repeat lymph node biopsy showed reactive lymphoid hyperplasia, with an increase in IgG-4 positive cells, and a significant increase in CD38+ and CD138 plasma cells in the interfollicular areas, with morphology consistent with Castleman disease (plasmacytic type)." (PMID 40696682, 2025).
cholera (1 paper, 2022). "In this study, we showed that during cholera, an acute bacterial enteric infection, MAIT cells in the duodenum are activated at levels significantly higher than that in the peripheral blood, based on CD38 expression." (PMID 35551522, 2022).
CNS lymphoma (1 paper, 2022). "Therefore, we propose that CD27 and CD38 should be incorporated into staining protocols for the detection of primary CNS lymphoma." (PMID 36153593, 2022).
colorectal tumors (1 paper, 2021). "Prognosis analysis indicated that those CRC patients with more CD38+ cells in the marginal area of colorectal tumors had better clinical prognosis." (PMID 33707428, 2021).
cystic teratoma (1 paper, 2018). "More detailed B cell analysis from the aspirate of a cystic teratoma confirmed presence of IgM, IgG, and IgD expressing CD19+ cells, in addition to less frequent CD27++CD38++ ASCs." (PMID 29406578, 2018).
cystoisosporiasis (1 paper, 2025). "Interestingly, the combination of reduced CD4+/CD8+ T-lymphocyte ratios and higher expression of HLA-DR+ CD38+ on CD4+ T-lymphocytes indicated increased immune activation in cystoisosporiasis patients." (PMID 40137697, 2025).
dementia (1 paper, 2024). Loss of intellectual abilities interfering with an individual's social and occupational functions. "Fourth, it was difficult to administer chemotherapy in the anti-CD38 mAbs-naïve group because of dementia." (PMID 39584925, 2024). "In the unadjusted analysis, patients who received anti-CD38 mAbs had significantly better demographic and clinical characteristics, including younger age, better performance status, a lower probability of dementia, a higher G8 level, and lower ADL and IADL scores." (PMID 39584925, 2024).
demyelinating disease (1 paper, 2019). A broad group of disorders that affect the myelin sheaths that cover the neurons. "CD38 and NAD+ in glial cells may have both beneficial and detrimental effects, and further studies to regulate the balance of these effects will make them potential targets for therapeutic intervention of MS and other demyelinating diseases." (PMID 31244614, 2019).
demyelination (1 paper, 2019). "In the current study, we examined the role of CD38 in CPZ-induced demyelination model in mice." (PMID 31244614, 2019). "In this study, we investigated the role of CD38 in CPZ-induced demyelination model." (PMID 31244614, 2019).